CD4 (CD4 molecule)
Diseases named in the same sentence as CD4 in open-access papers (continued):
Sharing a sentence is not in itself a finding about the gene and the disease.
colitis (continued). "In addition, miR-212/132(−/−) mice were highly resistant to colitis, which correlated with decreased Th17 cells and increased IL-10-producing CD4+ cells, thereby establishing a connection between these miRs and Tr1 regulatory cells." (PMID 33105907, 2020). "The colitis seen in the CD4-Cre+/TgMettl14FL/FL conditional knockout mice could be due to either hyperactive proinflammatory T cells or defective Treg cells that are unable to maintain homeostasis and prevent spontaneous inflammation." (PMID 32634481, 2020). "In this assay, adoptive transfer of CD45.1+ WT CD4+CD25− effector T cells into CD45.1+ RAG-1-KO mice led to colitis, and co-transfer of CD45.2+ Treg cells that are congenically different from effector T cells was used to evaluate the suppressive activity of Treg cells." (PMID 33024109, 2020). "To test this, we tried to induce colitis in mice colonized with a HD microbiota by transferring naive CD4+ T cells isolated from FoxP3-cre × Rorcfl/fl (RorcΔTreg) mice, from which no RORγt+ Treg cells can develop, but in which RORγt+ effector Th17 cells are preserved." (PMID 32817490, 2020). "Moreover, oral administration of a mixture of Clostridia strains known to induce CD4+ Foxp3+Tregs cells attenuated experimental colitis and allergic diarrhea." (PMID 33613446, 2020). "Interestingly, IL-17-producing CD4 T cells were also increased in the DSS-induced colitis mice by Al2O3 FPs; however, Al2O3 FPs treatment alone did not induce Th17 responses in the mice in vivo." (PMID 32993182, 2020). "Because we found that the colitis phenotype is likely due to dysfunctional Treg cells in the CD4-Cre+/TgMettl14FL/FL conditional knockout mice, we determined whether the colitis phenotype could be attenuated by antibiotics treatment." (PMID 32634481, 2020). "We hypothesized that circulating immune cells could mediate cross-talk between the lungs and colon, specifically, that chronic intratracheal OVA-induced colitis could be mediated by circulating activated CD4 T cells." (PMID 30949176, 2019). "ERα signaling increased CD4+ T cell proliferation and exacerbated colitis." (PMID 31849948, 2019). "Using a murine model of Citrobacter rodentium infection, we found the requirement of a functional IL-21/IL-21R signaling axis in the control of enteric microbial infections via augmenting activation of STAT1 in mucosal CD4+ T cells in a murine model of Citrobacter rodentium colitis." (PMID 30818341, 2019). "Experimental data showed that, in addition to colitis, scid/scid mice transferred with CD4+CD45RBHi T cells (CD45RB mice) developed osteopenia characterized with decreased total (trabecular and cortical) BMD, increased OC number in long bone surface and decreased number of OBs." (PMID 31847438, 2019). "CD4+T cell-transfer colitis models show chronic colitis with T cell infiltration, dependent on the microbiota, and may be superior to chemically induced models." (PMID 31417110, 2019). "Furthermore, the p-AMPK activity of colitis LP CD4+ T cells was significantly suppressed by combination AICAR and C.C. treatment in comparison to AICAR and increased in comparison to C.C.." (PMID 31417110, 2019). "To examine whether the inflammasome sensor NLRP3 may also be involved in this process, we evaluated the course of colitis in Rag1−/− mice receiving naïve CD4+ T cells sorted from the spleen of Nlrp3−/− mice." (PMID 31379813, 2019). "As TNFRs can be also expressed on CD4+Foxp3− T cells, the colitis model induced by naive CD4+ T cells could be a misleading." (PMID 30631042, 2019). "Moreover, similar to human CD, the TNBS-induced colitis model results in transmural inflammation, characterized by lamina propria infiltration with CD4-positive T cells, macrophages, and neutrophils." (PMID 30936867, 2019). "In addition, chronic exposure to IL-12 was reported to rather induce suppressive IL-10-production in CD4+ T cells, which further decreases the possible involvement of IL-12 in colitis." (PMID 30653608, 2019).
colitis (continued). "Similar to the results of previous studies, digoxin efficiently attenuated the colitis induced by adoptive transfer of CD45RB+ CD4 T cells by downregulating Th17 cytokines and receptors, such as IL-17A, IFN-γ, and IL-23R, but did not influence mucosal TNF-α expression." (PMID 30804707, 2019). "The role of Gab2/3 in macrophages during colitis development was next assessed, where 1 × 106 LPS-polarized BMDMs from Gab2/3−/− or WT were adoptively transferred into Rag2−/− mice first, and then sorted naïve WT CD4+ T-cells were transferred 24 h later." (PMID 30936879, 2019). "BBR-treated colitis LP CD4+ T cells showed suppressed OCR and ATP productions." (PMID 31417110, 2019). "In contrast, BBR-treated colitis LP CD4+ T cells showed elevated ECAR." (PMID 31417110, 2019). "Moreover, decreased number of CD4+CD25+Foxp3+ Tregs were observed in the mice with colitis at day 10 post-DSS induction." (PMID 31611558, 2019). "WT and Asc−/− Tregs equally restored colon length and thickness, and normalized stool consistency in mice also receiving WT CD4+ T cells, indicating that Asc−/− Treg cells are functional in vivo and can inhibit WT T-cell effector functions therefore preventing the onset of colitis." (PMID 31379813, 2019). "Moreover, a recent study demonstrates that induction of severe chronic remitting/relapsing UC-like colitis in immunocompetent mice requires not only IL23 and pathogenic CD4+ T cells in mLNs and colon, but also intestinal dysbiosis." (PMID 31191543, 2019). "Conversely, loss of Nlrp3 or Caspase-1 expression in CD4+ T cells did not confer a highly colitogenic phenotype in vivo in a T-cell adoptive transfer colitis model." (PMID 31379813, 2019). "Moreover, in a colitis mouse model, the adoptive transfer of Teff cells isolated from CD4+ specific Sirt1 knock-out mice resulted in a nearly 3-fold increase in iTreg formation compared with mice receiving WT Teff cells." (PMID 30792714, 2019). "In addition, TNFR2 expression by effector CD4+ T cells was required to induce full-fledged experimental colitis in one study." (PMID 29541073, 2018). "Moreover, they suppress the in vivo development of colitis induced in RAG-1−/− recipients by the transfer of naive CD4+ T cells in an IL-10-dependent manner." (PMID 29535721, 2018). "To confirm that Cnb1 deletion in CD11chighMHCII+ cells did not impact T-cell function in vivo, we monitored the development of colitis following adoptive transfer of naïve CD4+CD45RBhighCD25− T cells from Cnb1CD11c and Cnb1fl/fl mice into immune-deficient Rag2KO mice." (PMID 29549257, 2018). "After naive CD4+ T cells transfer, both WasdcDelRag2−/− and Rag2−/− mice developed severe colitis." (PMID 29725003, 2018). "Conversely, the transfer of NK1.1+NKG2D+CD4+ T cells exacerbated the colitis outcome." (PMID 29910814, 2018). "Importantly, conditional deletion of Gsk3β in CD4+ T cells was sufficient to prevent the development of colitis." (PMID 29382851, 2018). "Still, the percentage of IL-21+CD4+ T cells was lower compared to the AdTr colitis model." (PMID 29849593, 2018). "Meanwhile, Bifico could increase the colonic Foxp3 protein level, but decrease the colonic CD4 protein level in colitis mice." (PMID 29849501, 2018). "Third, these results suggested that Bifico might exert beneficial effects on experimental colitis by upregulating the number of Tregs and reducing total CD4+ T cells in both colonic tissue and peripheral blood." (PMID 29849501, 2018). "We conclude that deficiency of mPGES-1 in non-lymphoid tissues enhances colitis by reducing the generation of CD4+FoxP3+ T cells in the mLN and increasing pathogenic CD4+ T cells in the cLP." (PMID 30619314, 2018). "In addition, there was a decreasing trend of the colonic CD4 protein level in the pretreated-Bifico-colitis group compared with the colitis group (P = 0.639)." (PMID 29849501, 2018).
colitis (continued). "In addition, mesLN CD4+ T cells isolated from mice with colitis responded with excessive production of proinflammatory cytokines and chemokines following stimulation with exogenous IL-21." (PMID 29849593, 2018). "Furthermore, alpinetin significantly promoted expression of miR-302 but not others, and restrained expression of DNMT-1 and methylation level of Foxp3 promoter region in CD4+ T cells and colons of colitis mice." (PMID 30166541, 2018). "It has also been shown that miR-155 may aggravate colitis by directly inhibiting Th17 cell differentiation in CD4+ T cells or by regulating IL-10-producing B cells." (PMID 29774026, 2018). "Finally, the effects of this novel oral compound were evaluated in vivo using the CD4+CD45RBhigh T cell transfer colitis model." (PMID 30405600, 2018). "As control, we used IL-10neg CD4+ T cells, which induced severe colitis as expected." (PMID 30575716, 2018). "However, c-MAF overexpression within memory/effector CD4 T cells, normally containing T regulatory cells, augmented colitis when co-transferred with naïve Th cells." (PMID 29910812, 2018). "Absence of G9a in CD4+ T cells is associated with increased FOXP3 expression.G9a expression in CD4+ T cells is necessary for development of colitis in mice." (PMID 30619315, 2018). "Moreover, before treatment, studies were initiated; target validation was conducted to describe the dynamics of IL-21 protein expression by CD4+ T cells during the development of colitis." (PMID 29849593, 2018). "Furthermore, c-MAF overexpressing naïve CD4 T cells were unable to induce colitis as compared to WT controls." (PMID 29910812, 2018). "To determine how SCFA-GPR43 interaction regulates the function of Th1 cells and inhibits Th1 cell induction of colitis, we generated Th1 cells by culture of CD4+ T-cells from WT CBir1 and Gpr43−/− CBir1 Tg mice under Th1-polarizing conditions with IL-12 for 5-days for two cycles." (PMID 30177845, 2018). "Its submucosal layer predominantly consists of B cells and CD4+ helper T cells, which may be the priming site for the immune response in colitis." (PMID 30524476, 2018). "Unexpectedly, transfer of splenic IL-10-producing Foxp3neg CD4+ T cells caused colitis upon transfer, while small intestinal IL-10-producing Foxp3neg CD4+ T cells did not cause colitis as expected." (PMID 30575716, 2018). "In addition, we evaluated miR-146a levels in Rag1−/− mice transferred with CD4 + CD62L + T cells from regular donor mice i.e. lymphocyte transfer colitis." (PMID 30478292, 2018). "However, compared to WT or heterozygous controls, intestinal CD4+ T cells of Alpk1−/− mice were highly skewed towards a Th1 phenotype (IFN-γ+ IL-17A–) following induction of colitis, as measured by cell frequency and IFN-γ expression per cell." (PMID 30228258, 2018). "As well, the percentage of mesLN IL-21+CD4+ cells correlated with the degree of body weight change in individual mice with colitis, indicating that IL-21 may be involved in colonic disease development in this model." (PMID 29849593, 2018). "It is hence possible that PGE2 potentiates IL-23-mediated intestinal inflammation through enhancing EP4-dependent pathogenic CD4+RORγt+ responses, while in other instances and locations (like the mLN) it can induce CD4+FoxP3+ cells that protect from colitis development." (PMID 30619314, 2018). "Moreover, to determine if our methodology contributes to robust therapeutic value, candidate compounds require validation in multiple models (e.g., DSS-induced colitis, CD4+ T-cell adoptive transfer colitis, and IL-10 KO)." (PMID 30300381, 2018). "It is reported that MLN B cells protect mice from colitis induced by CD4+CD45RBhi T cells." (PMID 30539029, 2018). "On the other hand, CD4+ T cells are also important in the pathogenesis of colitis." (PMID 28361039, 2017).
colitis (continued). "In addition, H. pylori not only down-regulates Th17 and Th1 cytokine expression, but can up-regulate Th2 cytokine expression and increase the Th2:Th17 ratio of CD4+ T in the colonic mucosa of TNBS-induced colitis." (PMID 29088747, 2017). "Moreover, conventional CD4+ CD25+ Foxp3+ regulatory T cells were down‐regulated in mice with colitis." (PMID 27641629, 2017). "It is highly likely that reduction of cytotoxic CD8+ cell number with concomitant increase of CD4+ cells may be responsible for beneficial effect of smoking on severity of colitis." (PMID 28812128, 2017). "Colitis induced by oral administration of either dextran sodium sulfate or 2,4,6-trinitrobenzenesulfonic acid was exacerbated by HSD consumption and this effect was associated with increased frequencies of RORγt+ CD4+ T cells and neutrophils in the colon." (PMID 29379505, 2017). "Although it is still unclear whether the CD4 CTLs we observed in colitis are the same population/subset as recently described among CD4 IEL, both cells highly express CRTAM and possess killing function utilizing cytotoxic granules." (PMID 28280496, 2017). "As proinflammatory cytokines IFN-γ, IL-17A and granulocyte–macrophage colony-stimulating factor have been implicated in playing important roles in the development and pathogenesis of colitis, we investigated their production by CD4+ T cells from Bcl-3TOE mice compared with controls." (PMID 28452361, 2017). "However, transfer of NK1.1+ CD4+ NKG2D+ cells exacerbated colitis in mice, because of more shortened length and severe haemorrhage of colons." (PMID 28224733, 2017). "In conclusion, CD4+CD45RBhi-transfer colitis induces miR-142-5p." (PMID 29059189, 2017). "As regards MLN, macrophages could not be identified, while a moderate reduction in the number of lymphocytes, in particular of CD4+ T cells, was elicited by colitis." (PMID 29167641, 2017). "Thus, wogonin exacerbated DSS‐induced colitis by recruiting activated CD4+ and CD8+ cells into the colons." (PMID 27641629, 2017). "Finally, we confirmed that IFN-γ plays a substantial role in colitis induced by lung draining lymph node CD4+CD25− T-cell adoptive transfer (AT) in colitis-prone mice." (PMID 29163466, 2017). "Colonic NK1.1− CD4+ NKG2D+ T cells were inversely correlated with DSS‐induced colitis in mice." (PMID 28224733, 2017). "Phosphorylation of MLC2 leads to tight junction rearrangement, and reduction of intestinal barrier function, and CD4+CD45RBhi adoptive transfer into transgenic mice expressing constantly active MLCK resulted in a much more severe colitis compared with control mice." (PMID 28699686, 2017). "In these studies, administration of a specific NKG2D blocking antibody decreased NKG2D expression on CD4+ T cells, blocked the receptor on the other lymphocyte subsets and attenuated the development of colitis, highlighting NKG2D as a possible therapeutic target in IBD." (PMID 28926962, 2017). "In conclusion, we unveiled the role of IFN-γ+ CD4+ T cells on CS-mediated colitis in animal model." (PMID 29163466, 2017). "Consistent with reduced colitis, the frequency and absolute numbers of CD4+ T cells in the spleen, mesenteric LNs and lamina propria (LP) were significantly reduced in mice that had received T cells from Orai1fl/flOrai2−/−Cd4cre mice compared to WT or single knockout mice." (PMID 28294127, 2017). "NK1.1− CD4+ NKG2D+ T cells suppressed colitis induced by DSS in mice via production of TGF‐β." (PMID 28224733, 2017). "We found that in adoptive T cell transfer colitis, NHE3 deficiency and the associated dysbiosis dramatically accelerated and exacerbated colitis, increased mucosal CD4+ T cell and neutrophil homing, intestinal permeability, which was attenuated with broad-spectrum antibiotics." (PMID 27050757, 2016).
colitis (continued). "Consistent with the data obtained from chemical colitis models, the adoptive transfer of naive CD4+ CD45RBhigh T-cells into RAG-1−/− mice demonstrated that CCR5-deficent T-cells were unable to replicate the chronic colitis that was induced by CCR5-sufficient T-cells." (PMID 27492684, 2016). "CCR5 upregulation by colitis in CD4+ CD44low cells was abrogated by co treatment with maraviroc." (PMID 27492684, 2016). "However, in the same mouse colitis model, e.g., transfer of naive CD4 T cell-induced colitis, the opposite result was obtained in our study." (PMID 27601345, 2016). "There are some experimental studies performed on rodents showing preventive and/or therapeutic effect of pretreatment or treatment with EcN in colitis evoked by dextran sodium sulfate, trinitrobenzene sulfonic acid, or transfer of CD4+ CD62L+ T lymphocytes from BALB/c mice in SCID mice." (PMID 27433160, 2016). "Furthermore, our results are most compatible with the report that transfer of TNFR2-over expressing naive CD4 cells into lymphopenic mice led to an earlier wasting syndrome, a more severe colitis and augmented Th1 cytokine production." (PMID 27601345, 2016). "We next hypothesized that the protection against colitis observed in mice reconstituted with the high dose of CD25− splenocytes might be due to an increase of peripheral CD4+Foxp3+ regulatory T cell proportions." (PMID 27353032, 2016). "Interestingly, numerous unconventional Tregs of CD4+CD25−Foxp3+ were remarkably increased in the LPMCs of colitis mice followed by rSjcystatin injection compared to the mice with colitis." (PMID 26728323, 2016). "Accompanying the modifications in Treg status in IL-15koRAG2ko mice, which develop premature colitis following CD4+ T-cell transfer, we have found that the frequency and absolute number of total CD4+ T cells were significantly higher in the colon of IL-15-deficient mice." (PMID 26964669, 2016). "Type-I interferon secreted by pDCs has shown to support CD4+ Treg function and repress colitis." (PMID 26908454, 2016). "Indeed, CD4+ T cells have been shown to regulate neutrophil recruitment to the site of inflammation in a mouse colitis model." (PMID 27760272, 2016). "As a result, DEXA inhibited colitis induction may have been due to reduced donor CD4+ T cell survival in the Rag1-ko host." (PMID 27762297, 2016). "Considering the importance of the CD4+CD25−Foxp3+ T cell subset for the suppression of colitis, we decided to test if the severe colon disease observed in mice receiving the B cell-containing low-dose mixture was due to an insufficient number of regulatory T cell contaminants." (PMID 27353032, 2016). "CD4+ T lymphocytes obtained from 11-day-old neonates were compared with adult CD4+ T lymphocytes for their ability to mature and acquire effector function in an adoptive T-cell transfer colitis model." (PMID 26195040, 2015). "To investigate the potential role of Foxp3+ Tregs in the attenuation of DSS-induced colitis, we measured the number of CD4+ T cells isolated from mesenteric lymph nodes (MLNs) and spleens that express intracellular Foxp3 by fluorescence-activated cell sorting (FACS) analysis." (PMID 25910186, 2015). "CD4 T cells from reporter mice were injected into Rag1−/− hosts to induce colitis." (PMID 26834739, 2015). "DSS treatment of SIV-infected African green monkeys, a natural host species for SIV that does not manifest GI tract damage or chronic immune activation during infection, results in colitis with elevated levels of plasma SIV RNA, sCD14, LPS, CRP and mucosal CD4+ T-cell loss." (PMID 26282376, 2015). "To test if deficiency of EZH2 in Treg cells could alter the expansion of Treg and T effector cells in vivo, we also measured the percentages of Treg and T effector cells in the CD4 compartment at the end of colitis induction." (PMID 26090605, 2015).